ZIC2 (Zic family zinc finger 2)
Diseases named in the same sentence as ZIC2 in open-access papers (continued):
Sharing a sentence is not in itself a finding about the gene and the disease.
ependymoma (1 paper, 2022). A WHO grade II, slow growing tumor of children and young adults, usually located intraventricularly. "Material and Method: DNA methylation status of CDKN2A, RASSF1A, KLF4 and ZIC2 genes were quantitatively analyzed with pyrosequencing in 44 ependymoma tumor tissues." (PMID 34854470, 2022). "In this study, we showed that the ZIC2 gene is hypermethylated significantly in adult spinal ependymomas." (PMID 34854470, 2022). "In the present study, we analyzed the gene-specific methylation profiles of the CDKN2A, RASSF1A, KLF4 and ZIC2 genes in the ependymoma tumor tissues." (PMID 34854470, 2022). "Both ZIC2 and RASSF1A methylation status may be useful parameters in the subclassification of ependymomas." (PMID 34854470, 2022).
frontonasal dysplasia (1 paper, 2021). A group of rare bone development disorders characterized by an array of abnormalities affecting the eyes, forehead, and nose, and linked to midfacial dysraphia. "In the present study, we identified a de novo frameshift variant in ZIC2 for lethal frontonasal dysplasia in a Limousin calf." (PMID 33388042, 2021).
Goltz-Gorlin syndrome (1 paper, 2021). "OC15 carried a nonsense mutation (p.Arg95*) in PORCN, which is a gene responsible for Goltz-Gorlin syndrome, while OC15b carried an indel mutation in ZIC2 leading to the substitution of three residues by a proline (p.His404_Ser406delinsPro)." (PMID 33557041, 2021).
latent infection (1 paper, 2017). "Our findings uncover (i) a mechanism utilized by KSHV to maintain latent infection, (ii) a latency-lytic cycle switch operated by K-Rta, and (iii) a molecular mechanism of ZIC2-mediated local histone modification." (PMID 28835494, 2017). "We found that ZIC2, a transcriptional factor essential for stem cell pluripotency, plays a role in maintaining KSHV latent infection in naturally infected cells." (PMID 28835494, 2017). "Taken together, these results indicate that ZIC2 maintains the localization of the PRC2 complex through physical interaction and is required for PRC2-mediated deposition of H3K27me3 on the K-Rta promoter and, therefore, maintenance of latent infection." (PMID 28835494, 2017).
Opsoclonus (1 paper, 2024). "The humoral immunopathogenesis in paraneoplastic opsoclonus has been elucidated by the detection of a multitude of antineuronal antibodies: Ri, YO, Hu, Ma1, Ma2, amphiphysin, CV2, Zic2, and neurofilaments." (PMID 38883074, 2024).
Pan (1 paper, 2023). "As the representative transcription factor of ZIC family, the significant effect of ZIC2 in Pan cancer has been widely studied, which is a focal point having been paid close attention to by our study group 9." (PMID 37496990, 2023).
seminoma (1 paper, 2021). A radiosensitive malignant germ cell tumor found in the testis (especially undescended), and extragonadal sites (anterior mediastinum and pineal gland). "Our results suggest that ZIC2 expression is higher in many cancer groups, including the breast, cervical, colorectal, esophageal, gastric, head and neck, liver, lung, prostate and seminoma." (PMID 33665207, 2021).
situs inversus (1 paper, 2018). A congenital condition in which there is complete right-to-left reversal of the position of the major thoracic and abdominal organs (that is, they are arranged in a mirror image of the normal positioning). "Pulmonary situs was assessed in a total of 37 Zic2 mutant embryos, of these 73% showed right pulmonary isomerism, a single embryo exhibited left isomerism and none had situs inversus." (PMID 29992973, 2018).
tumor (40 papers, 2011 to 2026). "ZIC2 expression of ZIC2 was positively correlated with tumor mutational burden (TMB) and microsatellite instability (MSI)." (PMID 41694394, 2026). "The following series of phenotypic experiments showed that overexpression of UBE2C significantly rescued the decrease of tumor activity, cloning formation, proliferation, invasion, and migration caused by ZIC2 knockdown." (PMID 37496990, 2023). "In conclusion, our analysis suggested that ZIC2 displayed high expression in multiple tumors and was significantly associated with tumor progress and patient survival." (PMID 33665207, 2021). "The results were consistent with those observed in cohort I. Moreover, higher Zic2 protein expression was significantly associated with a poorer tumor phenotype, including larger tumor size, a higher rate of stage T3/T4 tumors, and higher AJCC stage." (PMID 34099631, 2021). "K-M curve showed that low expression of ZIC2 was associated with poor DSS time in CESC, and high expression of ZIC2 was associated with poor DSS time in the tumor of KIRP, LIHC and SARC." (PMID 33665207, 2021). "Meanwhile we also explored the correlation between ZIC2 expression and tumor mutation, immune microenvironment, and various tumor- and immune-related genes." (PMID 33665207, 2021). "Multiple tumor-related pathways were differentially enriched between high and low ZIC2 expression phenotypes in CRC, particularly the Wnt signaling pathway and stem cell-related pathways." (PMID 41694394, 2026). "GPC increased the stemness of OSCC tumor cells; ZIC2-regulated GPC metabolism through LYPLA2, inducing changes in the expression of the cancer stem cell markers Nanog and OCT4." (PMID 41856987, 2026). "The control vector-transfected CTBPH1 cells exhibited aggressive growth, while the MTF1 knockdown and ZIC2 CRISPR/cas9 knockout cells significantly inhibited tumor growth and reduced tumor weight." (PMID 40520016, 2025). "Inhibition of the MTF1/ZIC2 signaling axis arrests stem cell formation, thereby preventing the survival of cadmium-transformed cells and inhibiting tumor growth in xenograft models." (PMID 40520016, 2025). "Our findings extend this mechanism to BC, where overexpression of ZIC2 correlates with lymphatic metastasis and poor prognosis, suggesting a conserved role in tumor lymphangiogenesis." (PMID 40895068, 2025). "On the other hand, ZIC2 was demonstrated to repress tumor growth in breast cancer, and its reduced expression was correlated with short survival." (PMID 40952541, 2025). "Some other CpGs/genes differentiating these tumor groups were also engaged in neuronal processes (ZIC2, GNB1L)." (PMID 39456618, 2024). "Knockdown of ZIC2 resulted in reduced cell proliferation, invasion, migration, induction of G2/M phase arrest, and reduced tumor formation and lung metastasis in nude mice." (PMID 37496990, 2023). "Here, we first reported that high expression of ZIC2 triggered the secretion of MCSF in NPC cells, induced M2 polarization of tumor-associated macrophages (TAMs), and affected the secretion of TAM-related cytokines." (PMID 37479694, 2023). "In vivo experiments showed that ZIC2 silencing resulted in tumor growth inhibition, and overexpression of ZIC2 facilitated tumor growth." (PMID 37496990, 2023). "Overexpression of ZIC2 induced tumor growth in vivo, with the increase of JUNB, MCSF secretion, and CD163." (PMID 37479694, 2023). "Immunofluorescence also showed ZIC2 expression was indeed higher in the ccRCC tumor tissue than in the adjacent normal tissue." (PMID 37496990, 2023). "In particular, recurrent EGFR-amplified tumours showed increased expression of ZIC2, which is involved in increased cell proliferation, and increased expression of TFF1, which is involved in tumour cell migration." (PMID 36765632, 2023). "We also analyzed the relationship between tumor mutation burden (TMB), microsatellite instability (MSI), tumor microenvironment, tumor- and immune-related genes and ZIC2 expression." (PMID 33665207, 2021).
tumor (continued). "The results demonstrated that the ZIC2 mRNA levels in several tumor tissues were significantly different in different clinical stages." (PMID 33665207, 2021). "ZIC2 expression was strongly associated with the TMB, MSI, tumor microenvironment and tumor- and immune-related genes." (PMID 33665207, 2021). "At the end, we carried out the in vivo tumor-burdened experiment to reveal the role of LINC00665/miR-181c-5p/ZIC2 axis in the progression of LUAD." (PMID 34232917, 2021). "With the increase of tumor grade, the expression of ZIC2 also increased, especially in the tumor of ACC, KICH, KIRC, KIRP and TGCT (P < 0.05)." (PMID 33665207, 2021). "The GSEA revealed that multiple tumor- and immune-related pathways were differentially enriched in ZIC2 high or low expression phenotype." (PMID 33665207, 2021). "Subsequent silencing of ZIC2 expression in transformed cells inhibited spheroid formation, stem cell marker expression, and tumor growth in nude mice." (PMID 32066655, 2020). "Results showed that ZIC2 knockdown obviously inhibited tumor formation at all densities we tested, confirming the critical role of ZIC2 in maintaining CSCs traits in NCI-H1299 cells." (PMID 32922547, 2020). "Both the tumor volume and weight were significantly lower in the miR-129-5p mimic and si-ZIC2 groups than that in the blank and NC groups (p < 0.05)." (PMID 31649488, 2019). "We also found that inhibition of the MTF1/ZIC2 axis reduced tumor burden." (PMID 40520016, 2025). "Using CRISPR-Cas9 to knock out ZIC2 also prevented tumor formation in nude mice." (PMID 40520016, 2025). "This alignment between experimental and bioinformatics data validates ZIC2 as a reliable biomarker for BC and suggests its involvement in tumor progression and lymphatic metastasis through modulation of the tumor microenvironment, particularly lymphangiogenesis." (PMID 40895068, 2025). "Studies have revealed that ZIC2 exhibits high expression in PCa tissue, closely correlated with malignant tumor characteristics, including promoting cell migration, invasion, angiogenesis, and tumor initiation, while inhibiting cell apoptosis." (PMID 40353136, 2024). "Next, we explored the relationship between the expression of ZIC2 and clinicopathological features and found that the expression of ZIC2 was positively correlated with the age of onset, and gradually increased with the increase of tumor grade and stage (P < 0.05)." (PMID 37496990, 2023). "The results showed that ZIC2 was hypomethylated in the tumor tissues and hypermethylated in the adjacent tissues, which confirmed that the high expression of ZIC2 may be related to the hypomethylation of its promoter." (PMID 37496990, 2023). "Moreover, we also collected complete clinicopathological data sets from these databases and showed that ZIC2 expression increased with tumor stage, Fuhrman grade, pathological grade, and T stage." (PMID 37496990, 2023). "High ZIC2 expression was related to tumor recurrence (p = 0.022)." (PMID 37479694, 2023). "A lot of studies have reported that the overexpression of ZIC2 was significantly correlated with tumor migration, metastasis, angiogenesis or poor prognosis in patients, and it could be a potential tumor marker or therapeutic target." (PMID 33665207, 2021). "We demonstrated some potential mechanisms by which ZIC2 promoted tumor progression, and further suggested that ZIC2 may act as an oncogene with a strong effect in the processes of tumorigenesis and progression." (PMID 33665207, 2021). "Furthermore, the relationships between ZIC2 gene and tumor cell immune invasion and that between immune cell infiltration and the 5-year survival rate were studied using the tumor immune evaluation resource (TIMER) database." (PMID 33439969, 2021). "Finally, results from serial tumorigenesis experiments showed that ZIC2 overexpression greatly enhanced tumor formation capacity of NCI-H1975 cells at all densities we tested." (PMID 32922547, 2020).
tumor (continued). "Consistently, we found that protein expression of ZIC2 was also upregulated in tumor tissues." (PMID 32922547, 2020). "When ZIC2 was knocked down, the CCK-8 assay, colony formation assay, and EDU assay showed tumor activity, clonogenesis and proliferation were significantly decreased." (PMID 37496990, 2023). "ZIC2 overexpression induced the tumor growth of MC38 xenografts in vivo, and the addition of pexidartinib abrogates this induction, suggesting that ZIC2 augmented NPC tumorigenesis in vivo through MCSF secretion." (PMID 37479694, 2023). "And then, ZIC2 transcriptase-positively regulates UBE2C and activates AKT/mTOR signaling pathway to promote tumor malignant progression." (PMID 37496990, 2023). "We discovered that PAFAH1B3, ZIC2, and ESR1 were significantly different in tumor and normal tissues, which is consistent with the findings of the bioinformatic analysis." (PMID 37957420, 2023). "Together, our results indicated that ZIC2 induced M2 phenotype polarization of TAMs by regulating JUNB and MCSF in vivo, contributing to tumor development." (PMID 37479694, 2023). "Analyzes of the relationship between HHE genes and the tumor site in the colon region indicated that four genes, including DUSP4, ZIC2, CD55, and CLDN2 significantly increased in the cecum region (FDR < 0.01)." (PMID 36064367, 2022). "Given that, we explored the correlation of ZIC2 expression and TMB, MSL and tumor immune microenvironment." (PMID 33665207, 2021). "ZIC2, ZIC5, and C2 overlap in the age-dependent tumor-normal difference and age-related tumor-tumor comparisons." (PMID 28027300, 2016). "Cluster I consisted of genes upregulated in CC cells, which included tumor-related genes such as LGR4, AGR2, PCAF, TMEM97, FRAT2, EFNB2 and ZIC2." (PMID 21333016, 2011). "In addition, ZIC2 was reported to be an oncogene in ONGene database, while ZIC1 was listed as a tumor suppressor in TSGene database." (PMID 40952541, 2025). "The results of qRT-PCR and IHC analysis showed that PAFAH1B3, ZIC2, and ESR1 were differentially expressed in HCC and normal tissues and that patients with high TEXSRGs-scores had higher TEX infiltration abundance and tumor stemness gene expression." (PMID 37957420, 2023). "Due to the lack of availability of NPC mouse models, we subcutaneously injected ZIC2-overexpressing MC38 cells into C57BL/6 mice and served them as immunocompetent mouse tumor models to confirm that the function of ZIC2 in tumorigenesis is, at least in part, mediated through macrophage polarization." (PMID 37479694, 2023). "In particular, most of the mRMR genes (n = 7) were obtained from the differential gene expression analysis (DEA) comparing normal tissues versus primary tumor samples, with a larger number of upregulated genes, including the mRMR genes HHLA2, LINC01732, SAA1, AL353637.1, and ZIC2." (PMID 35565241, 2022). "In our study, we revealed that ZIC2 was highly expressed in LAC tumor tissues and indicated a poor overall survival of LAC patients, which suggested that ZIC2 may be a potential prognostic biomarker for LAC patients." (PMID 32922547, 2020). "Notably, we did not observe the direct association of TET3 with these factors, and found that several tumor suppressor genes (CDKN2B, ZIC2, and miR-196a) and oncogenes (PAX2, IL2RA, SOX11, and PAK7) were associated with TET3 in AML biology." (PMID 32209730, 2020). "ZIC2 expression was detectable and considered to be strong in 23.3% of cases and was absent in the majority of the tumours (76.7%)." (PMID 31640781, 2019). "Lastly, in the young.tumor versus old.tumor contrast, we identified five DEGs (ZIC2, ZIC5, ZNF439, USP54, and C2); this contrast may reflect differences in intrinsic tumor properties between tumors from the two age cohorts." (PMID 28027300, 2016).
tumor (continued). "Therefore, our study identified a novel therapeutic target for reversing drug resistance in LAC, and developing strategy to lower ZIC2 expression may increase the efficacy of cisplatin and paclitaxel treatment in LAC tumor." (PMID 32922547, 2020). "Interestingly, upon testing the in vivo potency of ZIC2+ versus ZIC2− cells in athymic mice, we observed tumor formation in mice injected with ZIC2+ cells but not in those injected with ZIC2− cells." (PMID 32066655, 2020). "Loss of ZIC2 expression was also linked to Gleason grade, advanced pathological tumour (pT) stage, lymph node metastasis and higher preoperative PSA levels in all cancers (p < 0.0001, each) and in the subset of ERG-fusion negative tumours (data not shown)." (PMID 31640781, 2019). "Thirdly, the high expression of ZIC2 may be related to the occurrence of cancer, while the low expression may be related to the development of cancer, which indicates that the gene ZIC2 does not play a role alone and may be passively and dynamically regulated in the process of tumor development." (PMID 33665207, 2021).